FOXC1 (forkhead box C1)
Diseases named in the same sentence as FOXC1 in open-access papers (continued):
Sharing a sentence is not in itself a finding about the gene and the disease.
microphthalmia (4 papers, 2009 to 2024). Congenital or developmental anomaly in which the eyeballs are abnormally small. "We therefore decided to investigate a wider role for FOXC1 in underlying developmental eye anomalies and screened the gene for disease-causing variations in a cohort of patients exhibiting anophthalmia, microphthalmia, and coloboma." (PMID 19626132, 2009). "However, on the basis of these results, it is unlikely that FOXC1 mutation is a major causative factor of anophthalmia, microphthalmia, and coloboma." (PMID 19626132, 2009). "The aim of this study is to establish whether mutation of FOXC1 contributes toward other developmental eye anomalies, namely anophthalmia, microphthalmia, and coloboma." (PMID 19626132, 2009). "Clinical sequencing and deletion/duplication analysis of PAX6, FOXC1, PITX2, and CYP1B1, as well as a clinical microphthalmia/anophthalmia gene panel, did not reveal causative variants." (PMID 33973683, 2021).
myocardial infarction (4 papers, 2020 to 2025). Gross necrosis of the myocardium, as a result of interruption of the blood supply to the area, as in coronary thrombosis. "The loci we associated with coronary artery disease (FOXC1), myocardial infarction (USP39), and atrial fibrillation (SLC35F1 and SSPN) through their effects on RHR have been associated with these cardiovascular diseases in recent studies." (PMID 37532724, 2023). "Further experiments need to investigate the impact of overexpression of FoxC1 within MSCs themselves, and how such genetic modification of MSCs could enhance their therapeutic potential for myocardial infarction." (PMID 34454602, 2021). "The role of FoxC1 in maintaining mesenchymal stem cell (MSC) niches after myocardial infarction (MI) has not been directly determined to date." (PMID 32963702, 2020).
pancreatic ductal adenocarcinoma (4 papers, 2015 to 2024). An infiltrating adenocarcinoma that arises from the epithelial cells of the pancreas. "Very recently, it was reported that FOXC1, a member of the family of forkhead box (FOX) transcription factors, was highly expressed in 85 patients with pancreatic ductal adenocarcinomas." (PMID 25875420, 2015).
cerebral small vessel disease (3 papers, 2021 to 2024). Cerebral small vessel disease is the term currently used to pathological processes that affect the brain parenchymal circulation (arterioles, capillaries, and veins). "Previous studies certified that FOXC1 mutations were associated with the defection of eye anterior segment and cerebral small vessel disease." (PMID 33941187, 2021). "Mutations in FOXC1 are associated with cerebellar malformation and cerebral small vessel disease." (PMID 37654790, 2023).
coloboma (3 papers, 2009 to 2025). An abnormality in which a part of a structure in one or both eyes is missing. "Ocular anomalies such as corectopia, posterior embryotoxon, colobomas, and iris clouding are well-established features of FOXC1-related ARS." (PMID 41487851, 2025).
colon adenocarcinoma (3 papers, 2020 to 2021). "For instance, a CTCF site near FOXC1 overlaps with recurrent deletions in esophageal, gastric and colon adenocarcinomas." (PMID 32024999, 2020).
congenital hydrocephalus (3 papers, 2009 to 2023). Hydrocephalus that is present at birth. "A spontaneous loss-of-FOXC1-function mutant mouse (named Foxc1ch/ch because it has congenital hydrocephalus) dies at birth and has skull and axial and appendicular bone defects, demonstrating a role for FOXC1 in intramembranous and endochondral bone formation." (PMID 37754840, 2023).
Corneal opacity (3 papers, 2011 to 2024). A reduction of corneal clarity. "How TFs like PAX6, p63, and FOXC1 regulate their target genes in LSCs and how their mutations give rise to LSCD and corneal opacities are not yet fully understood." (PMID 37856539, 2023). "PAX6, FOXC1, and p63 are known to be associated with corneal opacity, and FOSL2 is a novel corneal opacity gene identified in this study." (PMID 37856539, 2023).
developmental delay (3 papers, 2011 to 2023). "One FOXC1-related phenotype showed in OMIM was Axenfeld–Rieger syndrome, type 3, the features of which included hearing loss, CHD, dental anomalies, developmental delay, and a characteristic facial appearance, central nervous hypoplasia." (PMID 35518361, 2022). "Patient 9 also had developmental delay, which may or may not have been related to the deletion alone or in combination with p.P297S FOXC1." (PMID 21423868, 2011).
gastric adenocarcinoma (3 papers, 2016 to 2022). "In gastric adenocarcinoma, the forkhead box C1 (FOXC1) gene mediates the CSC phenotypes and tumor response to chemotherapy by regulating HH signaling." (PMID 36226253, 2022).
Hearing impairment (3 papers, 2016 to 2024). A decreased magnitude of the sensory perception of sound. "Deletions of FOXC1 were previously shown to account for a considerable proportion of individuals with anterior segment dysgenesis, who also presented with extraocular features such as hearing defects and mental retardation." (PMID 27124303, 2016).
Hodgkins lymphoma (3 papers, 2018 to 2019). A heterogeneous group of malignant lymphoid neoplasms of B-cell origin characterized histologically by the presence of Hodgkin and Reed-Sternberg (HRS) cells in the vast majority of cases. "The overexpression of FOXC1 has been consistently observed in the occurrence and development of Hodgkin's lymphoma." (PMID 29487724, 2018).
invasive breast carcinoma (3 papers, 2010 to 2022). A carcinoma that infiltrates the breast parenchyma. "We also found that FOXC1 was amplified in invasive breast cancer (8%)." (PMID 28028927, 2017).
iridogoniodysgenesis (3 papers, 2010 to 2016). "In contrast, FOXC1 and PITX2, which are mutated in both Axenfeld–Rieger syndrome and Iridogoniodysgenesis, are transcription factors that function in the NCC-derived POM to regulate development of the anterior segment." (PMID 27483349, 2016).
lung adenocarcinoma (3 papers, 2018 to 2023). A carcinoma that arises from the lung and is characterized by the presence of malignant glandular epithelial cells. "Long noncoding RNA CCAT2 might act as a competitive endogenous RNA (ceRNA) to regulate FOXC1 (encoding forkhead box C1) expression by competitively binding miR-23b-5p in lung adenocarcinoma." (PMID 36609391, 2023). "We analyzed FOXC1 expression in NSCLC based on information in the Cancer Genome Atlas (TCGA) database on UALCANC and found elevated FOXC1 expression in lung adenocarcinoma (LUAD) and lung squamous cell carcinoma (LUSC) compared to normal lung tissues." (PMID 30189871, 2018).
meningioma (3 papers, 2022 to 2026). A generally slow growing tumor attached to the dura mater. "All clusters and 12/12 meningioma-dura pairs exhibited hypomethylation of the gene promoters of a module associated with the craniofacial patterning transcription factor FOXC1 and its upstream lncRNA FOXCUT." (PMID 35769412, 2022). "Further studies are needed regarding the assessment of the response to anti-edematous therapies in low and high FOXC1 expressing meningiomas." (PMID 41632362, 2026). "There was a 251-fold higher (P = .01) expression of FOXC1 mRNA in a primary meningioma cell line from a 47-year-old patient with a grade III meningioma relative to dura from the same patient." (PMID 35769412, 2022). "Staining of dura from 4 patients and 9 meningiomas (4 grade I, 3 grade II, 2 grade III) showed a statistically significant difference in the percentage of cells expressing FOXC1 (dura vs I/II/III P < .001, I vs II P < .05, I vs II/III NS)." (PMID 35769412, 2022).
renal cell carcinoma (3 papers, 2016 to 2024). "However, there are currently no literature reports on the role of FOXC1 in renal cell carcinoma." (PMID 39093497, 2024).
rheumatoid arthritis (3 papers, 2020 to 2026). A chronic, systemic autoimmune disorder characterized by inflammation in the synovial membranes and articular surfaces. "Furthermore, FOXC1-mediated TRIM22 governs the excessive proliferation and inflammation of fibroblast-like synoviocytes implicated in rheumatoid arthritis via the NF-κB signaling pathway." (PMID 38041172, 2023).
blepharoptosis (2 papers, 2011 to 2025). "Mutations of the FOXC2 gene cause lymphedema-distichiasis syndrome - characterised by double rows of eyelashes, ptosis, photophobia and anterior segment anomalies reminiscent of those caused by FOXC1." (PMID 22022403, 2011).
brain malformations (2 papers, 2016 to 2023). "Based on their de novo occurrence and/or their established association with congenital brain malformations, we detected five disease-causing CNVs in four fetuses involving chromosomal regions 6p25.1-6p25.3 (FOXC1), 6q27, 16p12.3, Xp22.2-Xp22.32 (MID1), and Xp22.32-Xp22.33." (PMID 27087860, 2016).
cardiomyopathies (2 papers, 2017 to 2024). "Given that OBCSN mutations have not been linked to CHD, but could be potentially causing cardiomyopathies, we hypothesize that the NFATC1 missense variant along the FOXC1 variant is responsible for the cardiac phenotype." (PMID 28979898, 2017).
chronic obstructive pulmonary disease (2 papers, 2021 to 2023). A chronic and progressive lung disorder characterized by the loss of elasticity of the bronchial tree and the air sacs, destruction of the air sacs wall, thickening of the bronchial wall, and mucous accumulation in the bronchial tree. "Forkhead box C1 (FOXC1) is reported to attenuate the inflammation in chronic obstructive pulmonary disease, and homeobox 10 (HOXA10) is demonstrated to contribute to the innate immune response and suppress inflammation." (PMID 34277608, 2021). "Upregulation of FOXC1 resists apoptosis and inflammation in eye disease and chronic obstructive pulmonary disease (COPD)." (PMID 37184686, 2023).
De Hauwere syndrome (2 papers, 2023). "We conclude that haploinsufficiency of FOXC1 causes ARS and a broad spectrum of symptoms with variable expressivity that at its most severe end also includes a phenotype overlapping with De Hauwere syndrome." (PMID 37424725, 2023). "At the most severe end of the spectrum for FOXC1 disruption is De Hauwere syndrome, characterized by anterior segment anomalies, hypertelorism, short stature, hearing loss, hydrocephalus, joint hyperlaxity, and skeletal anomalies including hip dysplasia." (PMID 37895297, 2023).
endometriosis (2 papers, 2018 to 2021). The growth of functional endometrial tissue in anatomic sites outside the uterine body. "miR-106a-5p targets FOXC1 to exert an inhibitory effect on endometriosis (EMS) development, likely through the PI3K/Akt/mTOR signaling pathway." (PMID 34365889, 2021). "The top five key regulators in the miRNA-TF-gene network of endometriosis were FOXC1, FOXO1, miR-182-5p, miR-106a-5p, and CEBPA, which were directly connected to 117, 64, 57, 49, and 49 corresponding targets, respectively." (PMID 29357938, 2018). "Here, we identified four important FOX subfamily members, FOXO1, FOXC1, FOXL1 and FOXJ1, which cooperatively regulate the integrative networks in endometriosis." (PMID 29357938, 2018).
glioblastoma (2 papers, 2020 to 2021). The most malignant astrocytic tumor (WHO grade IV). "XIST RNA is upregulated in glioblastoma cells and its depletion inhibits glioblastoma angiogenesis by Zonula Occludens 2 (ZO-2) and Forkhead Box C1 (FOXC1) transcriptional inactivation." (PMID 32283739, 2020). "The sex chromosome dosage compensation lncRNA XIST is upregulated in glioblastoma cells, and its depletion inhibited glioblastoma angiogenesis via ZO2 (tight junction protein ZO-2) and FOXC1 (forkhead box C1) transcriptional inactivation." (PMID 34316694, 2021).
head and neck cancer (2 papers, 2021 to 2024). A primary or metastatic malignant neoplasm affecting the head and neck. "Within head and neck cancers, some functional and mechanistic studies have been published implicating FOXC1 in the biology of these tumors." (PMID 34540690, 2021). "Thus, information with regard to the prognostic role of FOXC1 in head and neck cancers is nascent at best, but does hold promise based on the findings of some initial studies on the functional significance of FOXC1." (PMID 34540690, 2021).
Hyperglycemia (2 papers, 2023 to 2025). An increased concentration of glucose in the blood. "The GL-3/FOXC1 pathway has been shown to protect HTR-8/SVneo cells from high glucose–induced apoptosis, suggesting that GL-3 and FOXC1 may play important protective roles in hyperglycemia during pregnancy." (PMID 41334450, 2025).
intracranial hemorrhage (2 papers, 2021 to 2025). Bleeding within the SKULL, including hemorrhages in the brain and the three membranes of MENINGES. "By mutating both zebrafish orthologs of human FOXC1, we show that foxc1a/b homozygotes display craniofacial dysmorphism, cardiac defects, and intracranial hemorrhage." (PMID 33530637, 2021).
ischemic cardiomyopathy (2 papers, 2024). Ischemic cardiomyopathy is a cardiomyopathy in which a weakness in the muscle of the heart due to inadequate oxygen delivery to the myocardium with coronary artery disease being the most common cause. "Further, to verify the correlation between telomere length and FOXC1/FOXC2, we performed TelC Q-FISH and immunohistochemistry staining on patient heart tissue chips consist of DCM (dilated cardiomyopathy), ICM (ischemic cardiomyopathy) and CHD (coronary atherosclerotic heart disease) biopsies." (PMID 38634789, 2024).
Juvenile glaucoma (2 papers, 2007 to 2023). Juvenile glaucoma (JG) is a rare autosomal dominant open angle glaucoma, characterized by early onset, severe elevation of intra ocular pressure of rapid progression, leading to optic nerve excavation and when untreated substantial visual impairment . "Mutations in the forkhead transcription factor (FOXC1) gene have been shown to cause juvenile glaucoma associated with a variety of anterior-segment anomalies." (PMID 17653043, 2007). "They found that MYOC (myocilin), FOXC1 (forkhead box C1), PITX2 (paired like homeodomain 2), and CYP1B1 (cytochrome P450 family 1 subfamily B) are both strongly implicated in juvenile glaucoma and ocular hypertension and highly expressed in TM and ciliary muscle cell types." (PMID 37138096, 2023).
ocular hypertension (2 papers, 2012 to 2023). Abnormally high intraocular pressure. "The contribution of common genetic variation at the FOXC1, TGFβ2, and BMP4 loci to risk of POAG was investigated in a case-control association study in 330 British Caucasian individuals comprised of 272 high-tension glaucoma (HTG) and 58 ocular hypertension (OHT), and 276 matched controls." (PMID 22736943, 2012).
oesophageal cancer (2 papers, 2022 to 2023). "PBX1 acted as pioneer transcription factor to mediate the binding of FoxC1 to ZEB2 promoter in oesophageal cancer cells." (PMID 35068042, 2022).
osteoarthritis (2 papers, 2025). A noninflammatory degenerative joint disease occurring chiefly in older persons, characterized by degeneration of the articular cartilage, hypertrophy of bone at the margins and changes in the synovial membrane. "Subsequently, EP300 binds to the FOXC1 promoter and promotes the enrichment of H3K27Ac at the FOXC1 promoter to elevate FOXC1 expression, ultimately regulating IL‐1β‐induced chondrocyte damage and promoting the progression of osteoarthritis." (PMID 40703976, 2025). "Chondrocyte abnormalities play an important role in osteoarthritis (OA), and forkhead box C1 (FOXC1) expression is related to OA progression." (PMID 40703976, 2025).
ulcerative colitis (2 papers, 2025). An inflammatory bowel disease involving the mucosal surface of the large intestine and rectum. "In this study, we identified FOXC1, GABPA, GATA2, and SUPT5H as key transcription factors implicated in the development of ulcerative colitis (UC) through the regulation of gene expression involved in inflammation, immune response, and epithelial barrier integrity." (PMID 41300749, 2025).
Wilms tumor (2 papers, 2011 to 2023). An embryonal neoplasm characterized by the presence of epithelial, mesenchymal, and blastema components. "Genes identified as targets of wild-type SIX1 in both Wilms tumor and hFK but not of SIX1-Q177R include established NPC-enriched genes FOXC1 and TMEM100, both of which were also found to be upregulated in SIX1/2-Q177R tumors." (PMID 37815464, 2023).
acute promyelocytic leukemia (1 paper, 2017). An aggressive form of acute myeloid leukemia (AML), characterized by arrest of leukocyte differentiation at the promyelocyte stage, due to a specific chromosomal translocation t(15;17) in myeloid cells. "We studied FOXC1 expression and function in acute promyelocytic leukemia (APL) and normal hematopoietic progenitors." (PMID 29137406, 2017).
acute respiratory distress syndrome (1 paper, 2021). Progressive and life-threatening pulmonary distress in the absence of an underlying pulmonary condition, usually following major trauma or surgery. "In a previous study, both ZDHHC19 and FOXC1 were found to be upregulated more than five times in neutrophils from patients with acute respiratory distress syndrome (ARDS) than in neutrophils from healthy volunteers." (PMID 33717105, 2021).
anterior synechia (1 paper, 2024). "In addition, anterior synechia was observed in eyes with mutations in PITX2, FOXC1, and FOXC2, which are required for anterior segment development and angiogenic privilege." (PMID 38263030, 2024).
arteriovenous malformations (1 paper, 2018). "Furthermore, knock-down of FOXC2 in combination with Etv2 has been shown to disrupt vascular development in the zebrafish and mouse embryo compound mutants for FOXC1 and FOXC2 display arteriovenous malformations." (PMID 29963552, 2018).
Arthritis (1 paper, 2020). Inflammation of a joint. "Silencing FoxC1 or enhancing miR-141-3p through intra-articular injection of siFoxC1/miR-141-3p agomir suppressed experimentally induced arthritis in rats by inhibiting SF proliferation and inflammation." (PMID 32373221, 2020).
autoimmune disease (1 paper, 2020). A disorder resulting from loss of function or tissue destruction of an organ or multiple organs, arising from humoral or cellular immune responses of the individual to their own tissue constituents. "Regulators in the FOX family are well-known regulators of cell proliferation, e.g., FOXC1 increases the proliferation of fibroblast-like synoviocytes in autoimmune diseases." (PMID 32721949, 2020).
brain injury (1 paper, 2022). Acute and chronic (see also brain INJURIES, CHRONIC) injuries to the brain, including the cerebral hemispheres, CEREBELLUM, and brain STEM. "The upregulation of FOXC1 has been shown to alleviate neuroinflammation in mice with ischemic brain injury." (PMID 36506580, 2022).
brain tumor (1 paper, 2020). "FOXC1 could play the essential role in brain tumor biology and patients with GBM." (PMID 32388501, 2020). "SOX6 and SOX13 could co-interact with FOXC1 and GATA2, which might lead to aggressive the brain tumors." (PMID 32388501, 2020).
cerebrovascular diseases (1 paper, 2024). "The TFs-gene regulatory networks identified the core TFs including PPARG, FOXC1 and GATA2, known for their roles in the inflammation regulation in the cerebrovascular diseases." (PMID 39469068, 2024).
childhood glaucoma (1 paper, 2025). "It is therefore unsurprising that the ocular phenotypes of PITX2-related disease are similar to those of FOXC1 and include childhood glaucoma associated with Axenfeld–Rieger anomaly and Peters anomaly." (PMID 41011222, 2025).
ciliopathy (1 paper, 2025). A genetic disorder of the cellular cilia or the cilia anchoring structures, the basal bodies, or of ciliary function. "DWS is classified as part of the ciliopathy spectrum, with mutations in genes such as ZIC1, ZIC4, and FOXC1 identified in familial cases." (PMID 41585016, 2025).